FOXI3 (forkhead box I3)
Description:
Transcription factor required for pharyngeal arch development, which is involved in hair, ear, jaw and dental development. May act as a pioneer transcription factor during pharyngeal arch development (By similarity). Required for epithelial cell differentiation within the epidermis (By similarity). Acts at multiple stages of otic placode induction: necessary for preplacodal ectoderm to execute an inner ear program (By similarity). Required for hair follicle stem cell specification (By similarity). Acts downstream of TBX1 for the formation of the thymus and parathyroid glands from the third pharyngeal pouch (By similarity).
Synonyms: CFM2
Tractability: No criterion of Open Targets' tractability assessment is met for any kind of drug.
Gene: Protein-coding gene on chromosome 2 (88,446,787 to 88,452,693, reverse strand). Ensembl gene ENSG00000214336.
Subcellular location: Nucleus
Gene Ontology:
Molecular function: DNA-binding transcription factor activity, RNA polymerase II-specific; RNA polymerase II cis-regulatory region sequence-specific DNA binding; DNA-binding transcription factor activity; sequence-specific DNA binding
Biological process: pharyngeal system development; anatomical structure morphogenesis; cell differentiation; epidermal cell fate specification; hair follicle development; odontogenesis of dentin-containing tooth; otic placode development; parathyroid gland development; regulation of transcription by RNA polymerase II; thymus development; regulation of DNA-templated transcription
Cellular component: nucleus
Genetic constraint (gnomAD): Loss-of-function variants: 4 observed, 12.53 expected, observed/expected ratio (o/e) 0.32, 90% interval 0.16 to 0.73. The upper end of that interval is the gene's LOEUF score, 0.73, which puts it in group 2 of 6, group 1 being the genes least tolerant of losing a copy. Missense variants: 489 observed, 512.59 expected, observed/expected ratio (o/e) 0.95, 90% interval 0.88 to 1.03. Synonymous variants: 238 observed, 228.91 expected, observed/expected ratio (o/e) 1.04, 90% interval 0.94 to 1.16.
Gene-disease validity (ClinGen):
ClinGen rates the evidence that FOXI3 causes each of these diseases.
T-cell immunodeficiency (autosomal dominant): Limited. A broad classification of disorders that affect the cell-mediated aspect of the immune response.
Homologues: Orthologues: macaque FOXI3 (99% identical), chimpanzee FOXI3 (95% identical), dog FOXI3 (89% identical), pig FOXI3 (87% identical), rat Foxi3 (75% identical), mouse Foxi3 (74% identical). Paralogues in human: FOXI2 (37% identical), FOXC2 (24% identical), FOXC1 (24% identical), FOXL1 (23% identical), FOXA2 (22% identical), FOXD1 (22% identical), FOXA1 (22% identical), FOXD3 (21% identical), FOXE3 (21% identical), FOXK1 (21% identical), FOXD2 (21% identical), FOXJ3 (21% identical), and 29 more.
Diseases named in the same sentence as FOXI3 in open-access papers:
FOXI3 is named in the same sentence as 20 diseases in open-access papers, as found by Europe PMC text mining. Sharing a sentence is not in itself a finding about the gene and the disease. The quoted sentences say what the papers report.
craniofacial microsomia (3 papers, 2023 to 2026). "Variants in FOXI3 have been implicated in craniofacial microsomia (CFM), yet the molecular mechanisms remain unexplored." (PMID 41639043, 2026). "In conclusion, we provide genetic, genomic, and biological experimental evidence that likely pathogenic FOXI3 variant alleles cause one form of Craniofacial Microsomia (CFM)." (PMID 37041148, 2023). "Recently, heterozygous pathogenic variants in FOXI3 have been associated with craniofacial microsomia, also known as Goldenhar syndrome, whose cardinal symptoms are microtia and craniofacial microsomia." (PMID 38137045, 2023).
ectodermal dysplasia (3 papers, 2012 to 2022). "As is known, this occurs due to a mutation in the FOXI3 gene, which causes the development of ectodermal dysplasia, and individuals with a mutant FOXI3 gene demonstrate hairlessness and are heterozygotes for this mutation." (PMID 36552399, 2022). "Foxi3 is mutated in several dog breeds, a condition described as canine ectodermal dysplasia." (PMID 26581094, 2015). "Furthermore, it has recently been shown that the loss of hair and teeth in Mexican and Peruvan hairless dogs (canine ectodermal dysplasia) is caused by a mutation in the Foxi3 gene, confirming a role for this gene in ectodermal differentiation." (PMID 22848601, 2012).
microtia (3 papers, 2023). "We term this genotype combination FOXI3 Mut/FOXI3 Mut; (ii) heterozygotes for a pathogenic variant and a modifier trans allele also show microtia (pedigree EUR01)." (PMID 37041148, 2023). "We studied a 5-generation kindred with microtia, identifying a missense variant in FOXI3 (p.Arg236Trp) as the cause of disease (logarithm of the odds = 3.33)." (PMID 36260083, 2023). "We subsequently identified 6 individuals from 3 additional kindreds with microtia-CFM spectrum phenotypes harboring damaging variants in FOXI3, a regulator of ectodermal and neural crest development." (PMID 36260083, 2023). "Parametric linkage analysis using a model accounting for variable penetrance showed statistically significant linkage between the FOXI3 p.Arg236Trp variant and microtia with a LOD score of 3.33." (PMID 36260083, 2023). "In this article, we report linkage analysis of a large kindred and association studies in 2 cohorts with microtia-CFM spectrum phenotypes showing that damaging variants in FOXI3 are responsible for a fraction of microtia-CFM cases." (PMID 36260083, 2023). "However, ectodermal disruption is a likely cause of microtia-CFM in patients with FOXI3 damaging variants." (PMID 36260083, 2023). "This 94.83 kb haplotype (from rs11686866 to rs111497808 including FOXI3) was present in heterozygosity in 7 of 25 (28%) CFM cases with types II or III microtia." (PMID 37041148, 2023). "Loss of function variants were found in patients with microtia and mandibular hypoplasia (CFM), suggesting dosage sensitivity of FOXI3." (PMID 36260083, 2023). "We studied 415 families with microtia/CFM, identifying 4 kindreds with damaging variants in FOXI3." (PMID 36260083, 2023). "In addition, the trans FOXI3 modifier haplotype is not present in the unaffected carrier father and brothers of family EUR01, while the proband with the combination FOXI3 p.Arg240Cys / FOXI3 modifier has microtia." (PMID 37041148, 2023). "This genotype combination is FOXI3 Mut / FOXI3 modifier; (iii) heterozygotes for a pathogenic variant and a non-modifier trans allele: there is no microtia in these cases; instead, the external ear could be normal or mildly dysmorphic." (PMID 37041148, 2023). "Additionally, haploinsufficiency is not the sole disease mechanism in FOXI3-linked microtia, as recessive inheritance has been demonstrated in a consanguineous Pakistani family." (PMID 38137045, 2023). "Furthermore, there were 16 cases from different pedigrees with a likely pathogenic FOXI3 variant without the modifier haplotype in which there was no microtia." (PMID 37041148, 2023). "However, there are also individuals who carry the FOXI3 modifier haplotype without severe microtia." (PMID 37041148, 2023).
breast carcinoma (2 papers, 2018 to 2021). "FOXI3 target genes also showed an association with metastasis in breast cancer." (PMID 30018953, 2018). "Examining FOXI3 expression in this data showed that breast cancers that metastasized to the bone often had high FOXI3 expression." (PMID 30018953, 2018). "Recent studies have demonstrated high expression of FoxI3 in bone metastases from prostate and breast cancers, suggesting that FoxI3 may promote bone metastasis and tumor growth and infiltration in the bone." (PMID 35153742, 2021).
prostate carcinoma (2 papers, 2018 to 2022). A carcinoma that arises from epithelial cells of the prostate gland. "Within the TCGA prostate cancer cohort, we find that FOXI3 expression increases with tumor stage." (PMID 30018953, 2018). "Almost all of the FOX genes were differentially expressed in prostate cancer, prostate carcinoma, and metastatic prostate cancer, except FOXA3, FOXB2, FOXC2, FOXI2, FOXI3, FOXP4, and FOXR1." (PMID 36292640, 2022).
22q11.2 deletion syndrome (1 paper, 2019). 22q11.2 deletion syndrome (DS) is a chromosomal anomaly which causes a congenital malformation disorder whose common features include cardiac defects, palatal anomalies, facial dysmorphism, developmental delay and immune deficiency. "Using mouse models, we found that two transcription factor genes, Tbx1, the gene for 22q11.2 deletion syndrome and Foxi3, genetically interact in the third pharyngeal pouch endoderm during thymus and parathyroid gland development." (PMID 31412026, 2019). "Together, we show that Tbx1 and Foxi3 are important for regulating PA segmentation through cellular and genetic mechanisms that may be critical in 22q11.2 deletion syndrome patients." (PMID 31412026, 2019). "We investigated whether Tbx1, the gene for 22q11.2 deletion syndrome (22q11.2DS) and Foxi3, both required for segmentation of the pharyngeal apparatus (PA) to individual arches, genetically interact." (PMID 31412026, 2019).
head and neck cancer (1 paper, 2018). A primary or metastatic malignant neoplasm affecting the head and neck. "While relatively few liver and thyroid cancers show elevated FOXI3 expression; other cancers display a wide range of FOXI3 expression across patient tumors (breast, lung, prostate, ovarian, and head and neck cancer)." (PMID 30018953, 2018).
tumor (3 papers, 2018 to 2023). "As such, we have utilized a variety of public data to examine FOXI3 across cancer types and test for association with key clinical measures of tumor progression." (PMID 30018953, 2018). "Understanding the intersect of the regulatory behavior of FOXI3 on factors prominent in hallmark processes of tumor progression to bone is essential to elucidating its role when these processes are hijacked and go awry." (PMID 30018953, 2018). "In support of this hypothesis, we noted that many of the genes shown to be downregulated with FOXI3 loss, also have demonstrated roles in tumor progression and metastasis, including bone metastasis." (PMID 30018953, 2018). "With this, we questioned whether changes in FOXI3 expression associate with features of tumor progression in several of these cancer types." (PMID 30018953, 2018). "Thus, we propose that when FOXI3 in tumor cells modulate the secretion of other bone factors including SPOCK1, Dlx, MAF, PthrP, HAS2, SVEP1, TGFβ3, and FGF which further primes the microenvironment, creates a crosstalk to help tumors grow in the bone." (PMID 30018953, 2018). "Further, in advanced cancer stage, during colonization of distant sites, FOXI3 may facilitate reconfiguring of the tumor microenvironment by expression of paracrine factors." (PMID 30018953, 2018). "Indeed, with governance of developmental features such as stem cell maintenance and involvement in EMT, FOXI3 may enable resistance to chemotherapy or tumor metastasis." (PMID 30018953, 2018). "At the primary tumor, FOXI3 may allow for stem cell maintenance or EMT; the latter in turn may implicate FOXI3 in tumor cell invasion into the local tissues and also into circulation." (PMID 30018953, 2018). "However, to date no studies have been published that demonstrate FOXI3's role in tumor progression." (PMID 30018953, 2018).
cancer (2 papers, 2018 to 2022). A tumor composed of atypical neoplastic, often pleomorphic cells that invade other tissues. "Given that many developmental pathways, transcription factors, and processes, are commonly implicated in cancer progression, we propose that FOXI3 may also play an important role in cancer." (PMID 30018953, 2018). "On the other hand, some FOX genes were specifically expressed in certain cancer types; for instance, FOXI3 is highly expressed only in GBM." (PMID 36292640, 2022). "In this review, we summarize the role of FOXI3 in embryogenesis and bone development and examine its potential role in cancer progression using an informatics approach." (PMID 30018953, 2018). "As a whole, this review highlights promising directions for research of FOXI3 and its potential roles in cancer progression." (PMID 30018953, 2018). "Using the cBioPortal to access multiple cancer types, we first interrogated FOXI3 expression across several major cancer types." (PMID 30018953, 2018). "In this review, we summarize the role of FOXI3 in embryogenesis and bone development and discuss its potential involvement in cancer progression with a focus on the bone metastasis." (PMID 30018953, 2018). "In this review, we note that FOXI3 a regulator of early bone development may play a potential role in cancer progression." (PMID 30018953, 2018). "Summary describing the role of FOXI3 in development and its hypothesized role in cancer progression." (PMID 30018953, 2018). "Based on our analysis of publicly available clinical data regarding FOXI3 expression in different cancer types and stages, we speculate that FOXI3 may have multiple roles throughout metastatic progression." (PMID 30018953, 2018). "FOXI3, a member of the Forkhead family affects embryogenesis, development, and bone remodeling; however, no studies have reported a role in cancer." (PMID 30018953, 2018).
retinopathy (1 paper, 2017). "Two of these were coding indel variants in the following genes: FOXI3 (chr17:38,032,793) and PROM2 (chr17:34,827,666), but neither are plausible candidates for retinopathy." (PMID 28813472, 2017).
FOXI3 also shares sentences with these, for which no sentence is quoted: goiter (1 paper); graft versus host disease (1); hypertrichosis (1); Kartagener Syndrome (1); lymphoma (1); lymphopenia (1); mandibular hypoplasia (1); metastatic prostate carcinoma (1); Oligodontia (1); thyroid cancer (1).